PDIA3 (protein disulfide isomerase family A member 3)
Description:
Protein disulfide isomerase that catalyzes the formation, isomerization, and reduction or oxidation of disulfide bonds in client proteins and functions as a protein folding chaperone. Core component of the major histocompatibility complex class I (MHC I) peptide loading complex where it functions as an essential folding chaperone for TAPBP. Through TAPBP, assists the dynamic assembly of the MHC I complex with high affinity antigens in the endoplasmic reticulum. Therefore, plays a crucial role in the presentation of antigens to cytotoxic T cells in adaptive immunity.
Synonyms: p58; ERp57; ERp60; GRP58; ERp61; GRP57; PI-PLC; HsT17083; ER60; HEL-S-269; HEL-S-93n
Tractability: Small molecule: it has a binding pocket of medium quality. Antibody: UniProt predicts a signal peptide or a membrane-spanning region. PROTAC: ubiquitination databases record sites on it; its protein half-life has been measured; a small molecule that binds it is known.
Target class: Isomerase; Enzyme
Gene: Protein-coding gene on chromosome 15 (43,746,394 to 43,773,279, forward strand). Ensembl gene ENSG00000167004.
Subcellular location: Endoplasmic reticulum; Endoplasmic reticulum lumen; Melanosome
Subcellular location (Human Protein Atlas): Endoplasmic reticulum
Pathways (Reactome):
Immune System: Antigen Presentation: Folding, assembly and peptide loading of class I MHC; ER-Phagosome pathway
Disease: Maturation of DENV proteins
Metabolism of proteins: Calnexin/calreticulin cycle
Gene Ontology:
Molecular function: identical protein binding; protein binding; protein disulfide isomerase activity; protein folding chaperone; protein-disulfide reductase activity; RNA binding; cysteine-type endopeptidase activity; disulfide oxidoreductase activity; phospholipase C activity; lncRNA binding
Biological process: peptide antigen assembly with MHC class I protein complex; protein folding; protein folding in endoplasmic reticulum
Cellular component: cell surface; endoplasmic reticulum; extracellular exosome; extracellular region; focal adhesion; melanosome; MHC class I peptide loading complex; nucleus; Tapasin-ERp57 complex; endoplasmic reticulum lumen; phagocytic vesicle; recycling endosome membrane
Genetic constraint (gnomAD): Loss-of-function variants: 6 observed, 27.81 expected, observed/expected ratio (o/e) 0.22, 90% interval 0.12 to 0.43. The upper end of that interval is the gene's LOEUF score, 0.43, which puts it in group 1 of 6, group 1 being the genes least tolerant of losing a copy. Missense variants: 307 observed, 368.62 expected, observed/expected ratio (o/e) 0.83, 90% interval 0.76 to 0.92. Synonymous variants: 119 observed, 133.29 expected, observed/expected ratio (o/e) 0.89, 90% interval 0.77 to 1.04.
Homologues: Orthologues: chimpanzee PDIA3 (100% identical), macaque PDIA3 (99% identical), pig PDIA3 (96% identical), rabbit PDIA3 (96% identical), dog PDIA3 (96% identical), guinea pig PDIA3 (96% identical), mouse Pdia3 (93% identical), rat Pdia3 (92% identical), tropical clawed frog pdia3 (71% identical), zebrafish pdia3 (70% identical), Drosophila melanogaster ERp60 (45% identical), Caenorhabditis elegans pdi-3 (44% identical), and 6 more. Paralogues in human: PDIA4 (41% identical), P4HB (31% identical), PDIA2 (28% identical), PDILT (22% identical), TXNDC5 (21% identical), PDIA5 (21% identical), PDIA6 (19% identical), TMX3 (17% identical), ERP44 (16% identical), TXNDC11 (16% identical), ERP27 (11% identical), TMX1 (10% identical), and 1 more.
Diseases named in the same sentence as PDIA3 in open-access papers:
PDIA3 is named in the same sentence as 193 diseases in open-access papers, as found by Europe PMC text mining. Sharing a sentence is not in itself a finding about the gene and the disease. The quoted sentences say what the papers report.
breast carcinoma (38 papers, 2014 to 2024). "PDIA3 has been strongly associated with various types of cancer as a prognostic biomarker (primary ductal breast cancer, prostate cancer, glioblastoma) and its overexpression is associated with poor outcomes of patients." (PMID 37960182, 2023). "In breast cancer cells, PDIA3 activity was implicated in regulation of cell spreading and migration." (PMID 35196163, 2022). "In vitro, differential transcriptome and proteome analyses of the bone metastasis-prone MDA-MB-231-BO2 breast cancer cell line versus parental MDA-MB-231 cells identified PDIA3 as a mediator of bone metastasis-associated proteins." (PMID 33095243, 2020). "Of related interest, depletion of PDIA3 in MDA-MB-231 breast cancer cells reduced chemoresistance-associated proliferation." (PMID 33095243, 2020). "The mannosylated peptide identified in mouse Pdia3, includes a conserved ProThr-motif that has been demonstrated to carry an O-linked mannose in PDIA3 from human breast cancer cells." (PMID 27812179, 2016). "Several publications have implicated PDIA3 with aggressive breast cancer (see introduction)." (PMID 36374169, 2023). "Furthermore, we observed an inverse association between CPNE1 (OR: 0.96, 95% CI 0.94–0.98) and breast cancer, while PDIA3 (OR: 1.19, 95% CI 1.10–1.30) were found to be associated with the risk of breast cancer." (PMID 37735436, 2023). "PDIA3 was also found to be a driver of anchorage-independent growth of breast cancer cells in mammospheres." (PMID 36374169, 2023). "In human breast cancer cell lines, knockdown of PDIA3 transcripts reduced cell proliferation and increased cell sensitivity to treatment with chemotherapeutic agents or irradiation." (PMID 36374169, 2023). "Analysis against human breast cancer tumor data sets implicates a clinical relevance of PDIA3 and the identified extracellular proteins to the basal subtype of breast cancer and to distant metastasis-free survival (DMFS) outcomes." (PMID 36374169, 2023). "Multiple studies have reported inhibition of cell proliferation and/or cell cycle progression in breast cancer cell lines upon pharmacological PDI-inhibition or PDIA3 silencing." (PMID 36912485, 2023). "To date, in vivo studies of PDIA3 in breast cancer have mostly explored its roles in metastasis, the major cause of mortality of patients with breast cancer." (PMID 36912485, 2023). "For example, proteomic analyses of breast cancers identified PDIA3 to be elevated in the tumors versus normal breast tissue and to be upregulated in invasive ductal breast cancers compared with lobular cancers." (PMID 36374169, 2023). "Laboratory data have shown a functional role of PDIA3 in breast cancer in vivo in mice or in promoting human breast cancer cell adhesion, spreading, and migration in vitro (Ref." (PMID 36374169, 2023). "Overall, the correlations of PDIA3 and transcripts encoding the extracellular proteins from our data set with DMFS in basal-type breast cancer implicate a clinical relevance to utilizing PDIA3 inhibition to reduce levels of these proteins." (PMID 36374169, 2023). "PDIA3 was required for the propensity of a metastatic subline of human MDA-MB-231 breast cancer cells for bone metastasis in a nude mouse model." (PMID 36374169, 2023). "Quantitative tandem-mass tag proteomics methodology was also used to identify proteins in the CM of MDA-MB-231 breast cancer cells that depend on PDIA3 activity, by comparison of proteins in the CM of control or 16F16-inhibited cells." (PMID 36912485, 2023). "PDIA3 was also essential for the propensity of a metastatic subline of human MDA-MB-231 breast cancer cells for bone metastasis in a nude mouse model." (PMID 37735436, 2023). "Calpain 2 (CAPN2) and protein disulfide-isomerase A3 (PDIA3) have been identified in exosomes derived from breast cancer cells." (PMID 36076942, 2022).
breast carcinoma (continued). "The dihydrotanshinone I (from Danshen, Salvia miltiorrhiza) was recently identified as a potential ERp57/PDIA3 inhibitor with an anti-breast cancer effect through the UPR pathway." (PMID 35109791, 2022). "A previous study found that PDIA3 expression was decreased by PDIA3 siRNA in human breast cancer cells, and this inhibitory effect was abolished by a p38MAPK-specific inhibitor (SB203580), suggesting that the expression of PDIA3 requires the p38 MAPK pathway." (PMID 35155431, 2022). "PDIA3 is expressed in various types of human cancers, including ovarian cancer, breast cancer, uterine cancer, lung cancer, gastric cancer, and hepatocellular carcinoma, and its expression is related to the prognosis and survival of various cancers." (PMID 36406049, 2022). "Studies have shown that PDIA3 expression is related to the prognosis of ovarian cancer, gastric cancer, renal cancer, laryngeal cancer, breast cancer, cervical cancer, lung cancer, and prostate cancer." (PMID 36406049, 2022). "PDIA1 and PDIA3 were the most abundant in cancer cell lysates and were also detected extracellularly in breast cancer cells (MDA-MB-231 and MCF-7)." (PMID 35725466, 2022). "(A) FACS analysis of total TAM isolated from EF43.fgf4-derived mammary tumors shows high levels of PDIA3 expression in a subpopulation of F4/80+CD11b+IL10highIL12low TAM." (PMID 34060472, 2021). "CM from WT-MEF supported spreading and F-actin organisation in all three breast cancer cell lines, whereas CM from Pdia3−/− MEF conferred a phenotype similar to FGM in basal lines and reduced F-actin structures in MCF-7 cells." (PMID 33095243, 2020). "Next, human breast cancer cell lines representing luminal and basal phenotypes were examined for PDIA3 and the related family member PDIA1 (33.7% sequence identity with 8% gaps for the human proteins) by immunoblotting." (PMID 33095243, 2020). "PDIA3 was also shown to be involved in EGF receptor signalling in MDA-MB-468 breast cancer cells and to promote growth of SUM159PT mammosphere cultures." (PMID 33095243, 2020). "In view that secreted products of WT MEFs were found to promote breast cancer cell spreading and motility and the CM of Pdia3−/− MEF had reduced activity, we next considered the effect of the pharmacological inhibitors on autocrine, secreted proteins." (PMID 33095243, 2020). "PDIA3 is up-regulated in invasive breast cancers and correlates in a mouse orthotopic xenograft model with breast cancer metastasis to bone." (PMID 33095243, 2020). "In breast cancer, PDIA3 was found by immunohistochemistry to be up-regulated in aggressive primary ductal breast cancers." (PMID 33095243, 2020). "Overexpression of PDIA3 is relevant to worse prognosis in cancers including laryngeal cancer, breast cancer, cervical cancer, and epithelial ovarian cancer." (PMID 32687065, 2020). "Overall, the data provide evidence for a role of protein disulphide isomerases including PDIA3 in promoting pro-migratory phenotypes in three breast cancer cell lines." (PMID 33095243, 2020). "The use of CM from WT or Pdia3−/− MEF specifically indicated a requirement for PDIA3 for fibroblast-secreted products that are supportive of MDA-MB-231 breast cancer cell spreading and migration." (PMID 33095243, 2020). "Together, these results implicate a role of protein disulphide isomerases in supporting pro-migratory phenotypes of breast cancer cells and indicate a functional importance of PDIA3-dependent secreted products." (PMID 33095243, 2020). "As an initial approach, two pharmacological inhibitors were used comparatively to implicate PDIA3 in in vitro behaviours of the three human breast cancer cell lines." (PMID 33095243, 2020). "O-Man glycans are also present in the conserved ProThr-motif of the mammalian Pdi1-homolog PDIA3 from human breast cancer cells, making Pdi1 a striking example that emphasizes the relevance of our findings." (PMID 26764011, 2016).
breast carcinoma (continued). "Although up-regulation of PDIA3 was reported in breast cancer and hepatocellular carcinoma tissues, to the best of our knowledge, it is the first time for detection of PDIA3 antibodies in plasma from PCa patients." (PMID 26581192, 2015). "Interestingly, the PDIs, PDIA1, ERp44, and PDIA3 (also known as ERp57), promote the anchorage-independent proliferation of breast cancer cells, a feature commonly found in transformed cells of solid tumours, facilitating mammosphere formation in vitro." (PMID 38891038, 2024). "Moreover, PDIA3 expression in fibroblasts enhances the pro-migratory properties of breast cancer cells in vitro." (PMID 38891038, 2024). "This demonstrates the relevance of PDIA3 as a prospective new molecular target in breast cancer." (PMID 36374169, 2023). "This interaction suggests that PDIA3 might promote the growth and proliferation of breast cancer cells by impacting the tyrosine kinase activity of human Epidermal Growth Factor Receptor 2 (HER2)." (PMID 37735436, 2023). "In recent years, there has been growing evidence of the potential therapeutic benefits of PDIA3 inhibition in various cancers, including clear cell renal cell carcinoma, drug-resistant ovarian cancer, breast cancer, hepatocellular carcinoma and in multidrug-resistant gastric cancer." (PMID 37686085, 2023). "Notably, the suppression of PDIA3 transcripts in human breast cancer cell lines was found to inhibit cell proliferation and increase cell sensitivity toward chemotherapy or radiation treatment." (PMID 37735436, 2023). "Notably, TNFRSF10B, GSTP1, and PDIA3 were found to interact with the target proteins of current medications used in prostate or breast cancer treatment." (PMID 37735436, 2023). "By analyzing heterogeneous intratumor subpopulations and metastatic sites, we demonstrated that FNDC1, A1BG, CANX, HSPA5, and PDIA3 may be key factors to tumor malignancy in a canine model of breast cancer." (PMID 34885011, 2021). "Notably, the Human Protein Atlas shows cytoplasmic expression of PDIA3 in human breast cancer cells." (PMID 34060472, 2021). "In a proteomic study of mammary glands from 21-day-old rats for proteins correlated with the cancer-preventative response of prepubertal consumption of genistein, PDIA3 was down-regulated, indicating a potential correlation of decreased levels with protection against development of breast cancer." (PMID 33095243, 2020). "The precise location of PDIA3 in breast cancer cells is of interest for future research." (PMID 33095243, 2020). "Overall, these results advance the concept that protein disulphide isomerases including PDIA3 drive the production of secreted proteins that promote a microenvironment favourable to breast cancer cell adhesion and motility, characteristics that are integral to tumour invasion and metastasis." (PMID 33095243, 2020). "Furthermore, PDIA3 has also been reported to be differentially expressed in various cancers, including breast carcinoma and ovarian cancer." (PMID 26745629, 2016). "PDIA3 can modulate the levels and activity of 17-β estradiol (E2) in breast cancer cells and may have a proliferative effect, promoting tumor growth." (PMID 27070597, 2016). "Thus, PDIA3 inhibition may offer a relevant new strategy to apply to this hard-to-treat subtype of breast cancer." (PMID 36374169, 2023). "Therefore, we hypothesize that combining PDIA3 inhibitors with tyrosine kinase inhibitors (such as Neratinib, Trastuzumab, and Pertuzumab) could enhance the inhibitory effect of tyrosine kinase inhibitors on breast cancer cells." (PMID 37735436, 2023). "Then, we studied the effects of inhibiting the most abundant isoforms, including PDIA1 and PDIA3 as well PDIA17 in cancer cells identified as high and low PDIA17 expressing breast cancer cells." (PMID 35725466, 2022). "In being selected for further studies on breast cancer cell lines, PDIA1 and PDIA3 were also present extracellularly (MDA-MB-231 and MCF-7)." (PMID 35725466, 2022).
breast carcinoma (continued). "More specifically, out of 21 members, PDIA1, PDIA3, PDIA4, and PDIA6 are identified to exhibit an increased mRNA level in breast cancer, according to the Gene Expression Atlas dataset." (PMID 35159012, 2022). "Consistent with the findings, the mRNA levels of PDIA1, PDIA3, PDIA4, and PDIA6 are typically overexpressed in HER2-enriched and Basal-like breast cancer subtypes as evidenced by gene expression data attained from the Gene Expression Atlas datasets." (PMID 35159012, 2022). "The simultaneous inhibition of PDIA1 and PDIA3 showed similar anti-proliferative effects in MCF-7 and MDA-MB-231 breast cancer cells." (PMID 35725466, 2022). "In addition, high expression of FNDC1 (probe 226930_at, p = 0.019) and the low expression of PDIA3 (probe 227033_at, p = 0.0037), HSPA5 (probe 230031_at, p = 0.0024) and CANX (probe 238034_at, p = 0.0013) were also associated with a worse overall survival in breast cancer patients." (PMID 34885011, 2021). "Accordingly, in our study, the low gene expression of calnexin, HSPA5, and PDIA3 had a significant prognostic value for OS and DMFS in human breast cancer patients." (PMID 34885011, 2021). "Lastly, we searched a publicly available single-cell transcriptome dataset of breast cancer and immune-infiltrating cells containing data from TNBC patients for PDIA3-expressing TAM." (PMID 34060472, 2021). "As a separate approach to investigate the functional role of PDIA3, we tested how CM produced from WT or Pdia3−/− MEFs, grown in serum-free FGM, would affect attachment or spreading of the breast cancer cell lines." (PMID 33095243, 2020). "Using SDS-PAGE, LC-MS/MS, and Western blot protein disulfide isomerase A3 (PDIA3) was identified and validated as overexpressed in breast cancer tissue." (PMID 24550697, 2014). "This includes not only those tumors in which ERp57/PDIA3 is putatively expressed on the cell surface membrane (i.e., T-cell leukemia 28 and breast cancer 29), but also in tumors expressing no significant cell surface ERp57/PDIA3." (PMID 38434963, 2024). "Based on breast cancer data sets in the TMNplot and GOBO databases, we confirmed that PDIA3 expression is elevated in invasive breast tumors and correlated with the clinical outcome of DMFS time for several breast cancer subtypes, confirming its relevance as potential new target." (PMID 36374169, 2023). "Protein disulfide isomerase A3 (PDIA3) is a disulfide oxidoreductase and isomerase of the endoplasmic reticulum that has known extracellular substrates and has been correlated with aggressive breast cancers." (PMID 36374169, 2023). "Another proteome analysis indicates that PDIA3 and PDIA6 show higher expression levels in invasive ductal carcinomas than in lobular carcinomas, and the high expression of PDIA3 and PDIA6 genes correlates with the aggressiveness of primary ductal breast cancer." (PMID 35159012, 2022). "In breast cancer mammospheres, the protein levels of PDIA1, PDIA3 (ERp57), and ERp44 are elevated." (PMID 35159012, 2022). "Finally, we introduce a ligand-directed AAVP-HSVtk platform for theranostics based on cell surface targeting of PDIA3 along with a mathematical model that reproduces the experimental dataset and estimates CSSTRESAC treatment outcomes in breast cancer." (PMID 34060472, 2021). "Finally, an independent validation showed FNDC1, A1BG, PDIA3, HSPA5, and calnexin as significant prognostic markers for human breast cancer patients." (PMID 34885011, 2021). "It remains to be established in further studies whether, apart from PDIA1, other PDIs including PDIA3, PDIA4 and PDIA6 displaying relative high expression in breast cancer cells and endothelium are also involved in regulating cancer cell interaction." (PMID 33023153, 2020).
breast carcinoma (continued). "We identified a cyclic peptide (CSSTRESAC) that specifically binds to a vitamin D receptor, protein disulfide-isomerase A3 (PDIA3) expressed on the cell surface of tumor-associated macrophages (TAM), and targets breast cancer in syngeneic TNBC, non-TNBC xenograft, and transgenic mouse models." (PMID 34060472, 2021).